EGFR (epidermal growth factor receptor)
Diseases named in the same sentence as EGFR in open-access papers (continued):
Sharing a sentence is not in itself a finding about the gene and the disease.
cancer (continued). "TcyDTDO activated ER stress and upregulated DR5 in T47D/EGFR cancer cells, but not T47D/vector cells." (PMID 31839995, 2019). "In addition to anti-PD-L1-IFN-α, we also generated an anti-EGFR-hIFN-α fusion protein and likewise, targeting human IFN-α to EGFR positive human cancer cells (Geo and H747) demonstrated superior IP-10 induction compared with controls." (PMID 31393905, 2019). "Testing nanoMIPs on different cancer cell lines, which expressed no or high amounts of EGFR, the double-imprinted polymer exhibited cytotoxicity, and apoptosis only in those cells that over-expressed EGFR." (PMID 31847103, 2019). "Our understanding of EGFR began from studying the function of wild-type EGFR using cancer cells and non-cancerous cells." (PMID 31508364, 2019). "Both TKIs and anti-EGFR mAbs are potent in inhibiting the tyrosine kinase activity of EGFR in cancer cells, however, oddly the responsive cancer types of these two kinds of anti-EGFR reagents do not overlap at all." (PMID 31508364, 2019). "The elevated EGFR levels could lead to the activation of several downstream signaling pathways, including the MAPK, PLCγ, STAT, and PI3K/AKT pathways, in cancer cells." (PMID 30770799, 2019). "Given that hypoxia blocked lysosome-mediated EGFR degradation, resulting in increased signaling, lysosomal activators should increase receptor degradation and potentially provide therapeutic benefit in anti-RTK cancer therapy." (PMID 31717697, 2019). "Epidermal growth factor receptor (EGFR) regulates ECM and promotes cancer invasion." (PMID 31552191, 2019). "This work demonstrates an alternative strategy to interrupt the aberrant EGFR-mediated phosphorylation cascade in cancer through authentic degradation of the receptor rather than strong inhibition of the tyrosine kinase site." (PMID 31374910, 2019). "Monoclonal antibodies (mAbs) targeting receptors of the Epidermal Growth Factor Receptor (EGFR) family, including anti-EGFR cetuximab and panitumumab and anti-ErbB2 trastuzumab and pertuzumab, are largely employed for cancer therapy in combination with other therapeutics." (PMID 32039017, 2019). "ErbB-1 (also known as EGFR, epidermal growth factor receptor) and ErbB-2 (also known as HER2, human epidermal growth factor receptor 2), are famous therapeutic targets for cancer treatment and their excessive signaling play critical roles in the development and malignancy of many tumors." (PMID 31510100, 2019). "CD133-EGFR interaction may activate MAPK/ERK and PI3K/Akt downstream signaling and CD133 mediated ligand independent EGFR activation may result in increased cancer cell proliferation, adhesion, migration, angiogenesis, and chemoresistance." (PMID 30467381, 2019). "Additionally, we found that BCAP31 participates in the distribution of active EGFR and that the regulatory roles of BCAP31 in EGFR intracellular recycling and cancer development are RAB11-dependent." (PMID 31588230, 2019). "Question 1: Given the fact that increased protein expression level of EGFR correlates with cancer progression and over-expression of wild-type EGFR is tumorigenic, why do wild-type EGFR expressing cancers not respond to TKIs?" (PMID 31508364, 2019). "Along these lines, EGFR and PI3K/AKT/mTOR pathway inhibitors in clinical use for other tumor types, such as Erlotinib and Afinitor, are under preclinical evaluation in HNSCC cancer." (PMID 31817001, 2019). "We discovered that EGFR dynamics could be used to differentiate the highly invasive cancer cell line (PC3) from the non- (LNCaP) and less (DU145) invasive cancer cell lines." (PMID 31805710, 2019).
cancer (continued). "We previously demonstrated that MT4-MMP is a key precursor and partner of Epidermal Growth Factor Receptor (EGFR), and enhances its activation leading to cancer cell proliferation in a non-proteolytic activity." (PMID 30654475, 2019). "Targeting of EGFR and HER2 is a proven anti-cancer strategy." (PMID 31286784, 2019). "Moreover, a previous study reported that EGCG also inhibits the activation of EGFR, human epidermal growth factor receptor 2 (HER2), and multiple downstream signaling pathways in cancer cell lines." (PMID 31636509, 2019). "In addition, erlotinib, a US Food and Drug Administration approved cancer drug which targets EGFR, was able to rescue MYST1‐promoted cell proliferation and EGFR signaling pathway." (PMID 31691527, 2019). "In addition, specific Grb7 peptides targeting the SH2 domain of Grb7, which blocks EGF/EGFR signal-mediated ERK activation, or knockdown of GRB7, which ablates MMP-9 expression, attenuate cancer invasion." (PMID 31083325, 2019). "Consequently, dual inhibition of EGFR and VEGFR-2 became helpful for targeting and treating cancer by acting synergistically." (PMID 32039146, 2019). "It is known that EGFR inhibitor-induced dAEs have major negative effects on the QOL of patients with cancer." (PMID 31049724, 2019). "It is widely known that EGFR and MET stimulate invasion of cancer cells." (PMID 31649529, 2019). "The stimulatory responses elicited in cancer cells by ligands of AHR like 3MC may involve a crosstalk of AHR with diverse signaling molecules and transduction pathways as EGFR, the transforming growth factor-β (TGF-β) and tumor necrosis factor-α (TNF-α)." (PMID 31370872, 2019). "Moreover, clinically 5 relevant resistance mechanisms were represented in EGFR, HER2, and ALK inhibitor-adapted cancer cell lines." (PMID 35582596, 2019). "Other processes altered under diabetic conditions point to a regulation of carcinogenesis, as the epidermal growth factor receptor (ErbB) and the PI3K–Akt signaling pathways, both in the upstream cascade of mTOR, and regulators of proliferation in several cancers including CC." (PMID 30628165, 2019). "The EGFR/MAPK/ERK signaling pathway has crosstalk with the Hippo/YAP signaling pathway and is involved in the positive regulation of YAP oncogenic function in various cancers." (PMID 31387256, 2019). "Sp1 and Sp3 regulate EGFR activity through interacting with HDAC1 and HDAC2 in cancer cells." (PMID 31196210, 2019). "In addition to JAK2 activation, EGFR-mediated FAK phosphorylation (Y925) and activation also promote migration and invasion of cancer cells." (PMID 31215502, 2019). "Henoch–Schönlein purpura (HSP) induced by anti-EGFR antibody was strongly suspected in one patient because the onset was during treatment with anti-EGFR antibody, not before or after the initial diagnosis of malignant tumor." (PMID 30646927, 2019). "Kinases such as EGFR and FGFR play a critical role in the proliferation of cancer cells." (PMID 31998131, 2019). "Here is worth just mentioning that a multitude of miRs and lncRNAs, as in other cancer types, appear down-regulated in NSCLC, including several EGFR-targeting miRs (miR-7, miR-27a-3p, miR-30, miR-34, miR-128, miR-133, miR-134, miR-145, miR-146, miR-149, miR-218, and miR-542-5p) and lcnRNAs." (PMID 31266248, 2019). "In contrast, some believe copy number gain (as oppose to amplification) of EGFR reflects chromosomal instability in cancer cells and has no biological significance." (PMID 31073965, 2019). "Beyond cancer cell‐expressed AREG in special cases, the TME‐derived AREG exerts an extra layer of chronic and long‐term pathological impacts on patients, including but not limited to development of acquired resistance to anti‐EGFR therapies such as cetuximab." (PMID 31493351, 2019).
cancer (continued). "In these samples, hierarchical clustering based on the expression of 1498 metabolic genes annotated in KEGG database showed the distinct expression pattern between EGFR-, FGFR- and RET-activated tumors, suggesting the distinct metabolic phenotypes in oncogenic RTK-driven cancer." (PMID 31221965, 2019). "The majority of EGFR positive cancers do not respond to TKIs nor to mAbs, e.g., non-small lung cancers expressing wild-type EGFR, representing the innate resistance to TKIs." (PMID 31508364, 2019). "Consistently, the observed growth dependency in EGFR- and FGFR-driven cancer could be recapitulated in vivo including PDX models that are believed to faithfully reserve the clinical features of patients." (PMID 31221965, 2019). "Furthermore, EGFR is also an upstream protein in the PI3K/AKT signal transduction pathway, which is an important target in cancer research." (PMID 31406500, 2019). "Interestingly, in line with our model of MET-independent EGFR-TKI drug escape, the resistant SCLC-transformed cancers demonstrated a similar increase in sensitivity to BCL-2 family inhibition." (PMID 31815659, 2019). "A second common event is activating mutations of KRAS, mutated in 40–50% of human CRCs, which stimulates cell growth by rendering cancer cells independent of epidermal growth factor receptor (EGFR) signaling." (PMID 31127094, 2019). "LINC00520-targeted EGFR inhibition might result in inactivation of the PI3K/Akt pathway, thereby inhibiting cancer development." (PMID 31890219, 2019). "There is no doubt that wild-type EGFR protein promotes cancer progression, but why do cancers expressing wild-type EGFR not respond to EGFR TKIs?" (PMID 31508364, 2019). "The aim of this study was to understand how EGFR inhibitors affect PDAC cells, and to determine if predictive biomarkers from other cancers could be adapted to PDAC." (PMID 30921351, 2019). "In addition to the B cell-based peptide cancer vaccines that target PD-1 and HER2, peptide mimics that can inhibit EGFR signaling have also been attempted." (PMID 31695802, 2019). "Question 2: Why does the phosphorylation status of EGFR not correlate with cancer progression nor with responsiveness to anti-EGFR drugs?" (PMID 31508364, 2019). "In the clinic, TKI is the first-line therapy for treating EGFR mutant positive cancer since most of the patients have fewer TILs and do not respond to immunotherapy." (PMID 31462678, 2019). "A variety of ATP-competitive EGFR/HER2 RTK dual inhibitors related to different scaffolds have been reported and many of them are currently in market or clinical trials for the treatment of cancer." (PMID 31286784, 2019). "It was shown in vitro that the bi-functional molecule inhibited growth of several cancer cell types that did not respond well to EGFR blockade or DR engagement as a stand-alone treatment." (PMID 31695800, 2019). "Examining the behavior of EGFR differential expression to proliferation markers in COAD, BRCA, GBB, and the Cancer Cell Line Encyclopedia (from the Broad Institute and Novartis, 877 samples) permitted identification of the inverse relationship in COAD and in the cell lines, but not in GBB or BRCA." (PMID 31857847, 2019). "The past 10 years have witnessed a growing body of evidence indicating that EGFR possesses pro-survival functions that are independent of its tyrosine kinase activity in cancer cells." (PMID 31508364, 2019). "In fact, a preclinical study demonstrated that the second-generation EGFR-TKI afatinib uniquely decreased EGFR activation, as well as that of HER2, HER3, HER4, and their downstream Akt phosphorylation, in heregulin-expressing cancer cells, overcoming heregulin-mediated resistance." (PMID 31862929, 2019). "We tested the impact of increasing dosage of TKIs on cell viability of non-treated (naïve) wt-EGFR-positive cancer cells." (PMID 31121829, 2019).
cancer (continued). "To investigate whether overexpression of MYC increases the sensitivity of cancer cells to DDAs, we engineered MCF10A human mammary epithelial cells to overexpress EGFR, MYC, or both proteins using retroviral vectors." (PMID 31839995, 2019). "Question 3: Why do the TKI responsive cancers not overlap with the anti-EGFR mAbs responsive cancers?" (PMID 31508364, 2019). "In this regard, recent data have demonstrated that a potent TKI of EGFR, erlotinib, in combination with the glutaminase inhibitor CB-839 severely affects metabolic and energetic balances, leading to apoptotic death of NSCLC cancer cells." (PMID 31374910, 2019). "We found that miRNA-145 was markedly suppressed the expression of EGFR and inhibited the cancer cell growth, relative to blank control and negative control miRNA (p<0.05)." (PMID 31554377, 2019). "In cancer cells, decorin decreases the expression of VEGFA and HIF-1α through interfering with the signaling pathways of Hepatocyte Growth Factor (HGF/Met) and epidermal growth factor receptor (EGFR)." (PMID 31428311, 2019). "In this study, using wt-EGFR-expressing cancer cells A549 (lung), DU145 (prostate), PC3 (prostate), and MDA-MB-231 (breast), we characterized the TKI-induced dimerization status of EGFR and determined the dependency of cells on kinase-inactivated EGFR for survival." (PMID 31121829, 2019). "In this study, we observe that the attenuation of EGFR’s kinase activity had no impact on overall survival of the wt-EGFR-expressing cancer cells." (PMID 31121829, 2019). "It is important to note that cancer cells frequently over-express EGFR with defective negative feedback responses; characteristics that are not a feature of normal human cells." (PMID 30287279, 2019). "In the p16 positive carcinomas, Ktrans max correlated with VEGF expression (ρ = 0.46, P=0.04), Ktrans kurtosis correlated with Hif1-alpha expression (ρ = 0.46, P=0.04) and Ktrans entropy correlated with EGFR expression (ρ = 0.50, P=0.03)." (PMID 30718984, 2019). "In epithelial carcinomas, ST6GAL1 expression confers increased resistance to chemotherapy, hypoxia, and nutrient deprivation by promoting a stem-like phenotype, bolstering signaling through pro-survival and pro-proliferative EGFR, HIF-1α, and NF-κB pathways." (PMID 31408003, 2019). "Furthermore analysis of clinic specimens revealed increased expression of MICAL‐L2 in carcinoma tissues and a positive correlation between MICAL‐L2 and EGFR expression levels." (PMID 31034158, 2019). "In p16 positive carcinomas, Ktrans max correlated with VEGF expression (p=0.46, P=0.04), Ktrans kurtosis correlated with Hif1-alpha expression (p=0.46, P=0.04), and Ktrans entropy correlated with EGFR expression (p=0.50, P=0.03)." (PMID 30718984, 2019). "Likewise, Epidermal Growth Factor Receptor (EGFR) signaling, which is altered in many cancers, regulates YAP/TAZ activity." (PMID 29642615, 2018). "Sex, EGFR, and subject age were also informative, while cancer history and nodule location were least informative and not included in the parsimonious model." (PMID 32913898, 2018). "Another signaling pathway such as WNT, TGFβ, PI3K/Akt, EGFR, and JAK/STAT, as well as transcriptional regulators including OCT4, Nanog, YAP/TAZ, and Myc are also commonly activated in various cancer stem cells to regulate their self-renewal and differentiation state." (PMID 29681949, 2018). "Nevertheless, the reason why above mechanism has not been reported in other EGFR mutant cell lines and cancers is not clear so far." (PMID 29455669, 2018). "In the setting of MET‐addicted cancers, our work anticipates that assessing ERRFI1 and miR‐205 expression could guide the identification of patients that develop adaptive EGFR‐driven resistance to MET‐TKIs." (PMID 30021798, 2018).
cancer (continued). "Each microdissected sample was also tested for cancer hotspot mutations on KRAS, BRAF and NRAS genes, and for the T790M EGFR resistanc e mutation, but no mutation was found." (PMID 29492209, 2018). "As the newly-appreciated Fas survival signaling is a significant contributor to cancer cell survival and aggressiveness, we turn our focus toward the relationship between Fas non-apoptotic signaling and EGFR signaling in cancer." (PMID 30127519, 2018). "If a mutation has activated EGFR, activating RAS mutations have little additional growth effect, and do not spread through the population of cancer cells." (PMID 29854275, 2018). "Similarly, many cancer types including breast often acquire resistance to various RTK inhibitors such as VEGFR inhibitors (bevacizumab), EGFR inhibitors (gefitinib), FGFR inhibitors (AZD4547)." (PMID 29455658, 2018). "Cancer cells up-regulate the rate-limiting enzymes of glycolysis such as GLUT1, HK2, PKM2, and LDHA as a result of the expression of oncogenes including RAS, SRC, or EGFR." (PMID 29559564, 2018). "Importantly, MR30 showed significantly stronger potency than the clinical EGFR inhibitor gefitinib or the equimolar combination of EGFR and MGMT inhibitors (gefitinib + O6-BG) on 5 out of 7 EGFR expressing cancer cell lines (p<0.01)." (PMID 30416678, 2018). "The main function of anti-EGFR MoAbs is to compete with endogenous ligands for binding to EGFR, thereby blocking downstream RAS and MAPK signaling pathways, inhibiting proliferation of cancer cells, and prolonging the survival of patients with advanced cancer." (PMID 30416987, 2018). "Hu-rhEGF-rP64k/Mont cancer vaccine can induces a neutralizing antibody-mediated immune response, against the normal circulating self-protein antigen Epidermal Growth Factor (EGF), which is the main ligand of the Epidermal Growth Factor Receptor (EGF-R)." (PMID 29661145, 2018). "Many cancer cells contain a protein called epidermal growth factor receptor (EFGR) on its surface that mainly is not found in healthy cells in the human body." (PMID 34466436, 2018). "Specifically, OPC patients with HPV16-positive and EGFR negative cancers present better OS prognosis than patients with HPV-negative and EGFR positive cancers." (PMID 30619735, 2018). "Studies over the past few years have revealed that EGFR promotes cancer cell survival through mechanisms that are independent of its tyrosine kinase activity." (PMID 29358623, 2018). "In this study, for the first time, we have shown that EGFR suppresses mitophagy by a mechanism that is independent of its tyrosine kinase activity, and activation of mTORC2 induces mitophagy in cancer cells." (PMID 29358623, 2018). "The observed EGFR expression was validated through flow cytometry and compared with lung H520 cancer cells, which are EGFR-negative." (PMID 30068339, 2018). "Furthermore, we found that LRIG2 unexpectedly phosphor-activates phosphoinositide 3-kinase (PI3K)/AKT and epidermal growth factor receptor (EGFR), which are conventionally accepted as survival signaling cues in diverse types of cancer." (PMID 29358688, 2018). "Nevertheless, there is limited evidence supporting the role of anti-EGFR therapy in HPV-related cancers, as alteration in EGFR levels in OPCs does not correlate with HPV status, and clinical data remain controversial." (PMID 30619735, 2018). "In addition to EGFR, cancer stem cells have also been shown to be responsive to other TKI treatment which further triggered cancer cell death." (PMID 29455663, 2018). "Efforts to target EGFR with monoclonal antibodies (cetuximab) and small molecule inhibitors (gefitinib and erlotinib) have been extensively investigated in adult cancers leading to FDA approval for some EGFR overexpressing cancers." (PMID 29552283, 2018).